RBBP8 (RB binding protein 8, endonuclease)
Diseases named in the same sentence as RBBP8 in open-access papers (continued):
Sharing a sentence is not in itself a finding about the gene and the disease.
bladder tumors (2 papers, 2018 to 2022). "In contrast, 71.4% (n = 30/42) of the analyzed bladder tumors exhibited a significant loss of RBBP8 protein expression in the nuclei with an IRS score below 3 (median IRS, 0)." (PMID 29445424, 2018). "In line, a statistically inverse correlation between nuclear RBBP8 protein level and RBBP8 promoter methylation was confirmed, supporting a contribution of epigenetic RBBP8 alterations to its protein loss in primary bladder tumors." (PMID 29445424, 2018). "Overall, 137 out of 368 (37%) analyzed bladder tumors exhibited a tumor-specific RBBP8 promoter methylation." (PMID 29445424, 2018). "RBBP8 protein expression was characterized in normal urothelium and in bladder tumor tissues using immunohistochemistry." (PMID 29445424, 2018). "A significant downregulation of RBBP8 protein expression in nuclei was demonstrated for bladder tumors with an increased RBBP8 promoter methylation (> 5%) compared to those with a low RBBP8 methylation." (PMID 29445424, 2018). "Classifying tumor samples by subtype, i.e., “luminal,” “basal,” and “SCC-like,” RBBP8 promoter methylation tended to be enriched in luminal-type bladder tumors." (PMID 29445424, 2018). "Based on MSP and bisulfite-pyrosequencing, RBBP8 methylation was assessed in an independent cohort of primary bladder tumors." (PMID 29445424, 2018). "RBBP8 methylation frequency was increased to 39.1% (9/23) in primary bladder tumors." (PMID 29445424, 2018). "Interestingly, low-grade non-invasive bladder tumors retained high levels of RBBP8 protein within the nucleus." (PMID 29445424, 2018). "However, a significant increased RBBP8 promoter methylation was observed for high-grade bladder tumors, including pTa high-grade carcinomas, (mean methylation 20.9%; s.d. ± 4.4%) compared to low-grade BLCA (mean methylation 2.4%; s.d. ± 1.4%)." (PMID 29445424, 2018). "Cytoplasmatic RBBP8 protein expression remained visible in all bladder tumors (median IRS, 8)." (PMID 29445424, 2018). "Stratifying the tumor samples by substage, we revealed that the observed loss of nuclear RBBP8 protein significantly correlates with advanced invasive (pT1-pT4) bladder tumors, while pTa non-invasive tumors did not significantly differ in cytoplasmic and nuclear RBBP8 protein level." (PMID 29445424, 2018). "We identified that RBBP8 and MSH4 were the most significantly hypermethylated genes in bladder tumors than in normal tissues (p < 0.001 and p = 0.016, respectively)." (PMID 36076047, 2022). "Classifying the bladder tumors by papillary and invasive subtype, no clear differences in RBBP8 promoter methylation were detected." (PMID 29445424, 2018).
breast tumor (2 papers, 2013 to 2016). "We therefore analyzed the effects on CtIP/RBBP8 levels at the time of the biopsy in response to tamoxifen in luminal breast tumors." (PMID 24403251, 2013). "However, CtIP/RBBP8 relevance in breast tumor appearance, development, and prognosis has yet to be established." (PMID 24403251, 2013). "They analyzed the response to tamoxifen of 59 nonoperable ER+ breast tumors and found that the lower the expression of CtIP/RBBP8, the lower the tumor size reduction." (PMID 24403251, 2013).
hepatocellular carcinoma (2 papers, 2023 to 2024). A malignant tumor that arises from hepatocytes. "Further, in situ, RBBP8 and ATF4 expression levels were analyzed by co-immunostaining in tumor samples from hepatocellular carcinoma patients." (PMID 37591836, 2023).
benign prostatic hyperplasia (1 paper, 2018). A non-cancerous nodular enlargement of the prostate gland. "Interestingly, RBBP8 mean methylation of control urines from patients diagnosed with cystitis and benign prostatic hyperplasia (BPH) was nearly similar to healthy controls." (PMID 29445424, 2018).
hereditary cancer (1 paper, 2013). Malignant neoplasms occurring in families at a rate greater than that expected by chance and caused by germline mutations in a specific gene. "Despite this relationship, no CtIP/RBBP8 mutations have been observed so far in families with hereditary cancer but that are wild type for BRCA1 and BRCA2." (PMID 24403251, 2013).
liver cancer (1 paper, 2023). An epithelial or non-epithelial malignant neoplasm that arises from the liver. "RBBP8 expression was also analyzed in multiple liver cancer cell lines at basal or cell cycle synchronized cells, showing that RBBP8 was positively associated with ATF4 expression at the protein level." (PMID 37591836, 2023). "Besides, RBBP8 was positively associated with ATF4 expression in liver cancer." (PMID 37591836, 2023). "RBBP8 or ATF4 protein expression were potentially diagnostic markers and therapeutic targets of liver cancer." (PMID 37591836, 2023). "TCGA database showed that both RBBP8 and ATF4 mRNA levels were highly expressed in multiple cancer types, including liver cancer, and demonstrated its association with a shorter life span in HCC patients, and RBBP8 expression was highly expressed in either Ki67-positive regions or positive cells." (PMID 37591836, 2023). "Thus, liver cancer provides a model to study the physiological roles of RBBP8 and ATF4 in human disease." (PMID 37591836, 2023). "Interestingly, overexpression of RBBP8 in vitro promoted ATF4 activation under ER stress, and RBBP8 expression showed a positive correlation with ATF4 expression in liver cancer tissues by co-immunostaining." (PMID 37591836, 2023). "To study the pathological role of RBBP8 in regulating ATF4 activity, we illustrated that both RBBP8 and ATF4 were highly expressed in liver cancer tissues compared with healthy controls and highly expressed in Ki67-positive proliferating cells within the tumors." (PMID 37591836, 2023).
lymphoma (1 paper, 2020). A malignant (clonal) proliferation of B- lymphocytes or T- lymphocytes which involves the lymph nodes, bone marrow and/or extranodal sites. "Inactivation of one RBBP8 allele predisposed mice to multiple types of cancers (e.g., lymphoma) suggesting that RBBP8 functions as a tumor suppressor." (PMID 33519915, 2020).
schizophrenia (1 paper, 2024). A major psychotic disorder characterized by abnormalities in the perception or expression of reality.
seminoma (1 paper, 2018). A radiosensitive malignant germ cell tumor found in the testis (especially undescended), and extragonadal sites (anterior mediastinum and pineal gland). "In turn, a few urines from young patients with a testicular neoplasm (mostly seminomas) showed an increased mean RBBP8 methylation." (PMID 29445424, 2018).
urothelial carcinoma (1 paper, 2018). A malignant neoplasm derived from the transitional epithelium of the urinary tract (urinary bladder, ureter, urethra, or renal pelvis). "RBBP8/CtiP has a proven role in homologous recombination-mediated DNA double-strand break repair (HR and NHEJ pathway), impairment of which reduces DNA repair fidelity and may promote genome instability also in urothelial carcinomas." (PMID 29445424, 2018).
ZIKV infection (1 paper, 2021). "Dysregulation of the neuronal genes, such as RBBP8, ASPM, AXL, TBR2, MCPH1, and CENPF upon ZIKV infection may cause different neurological or brain development related disorders." (PMID 33891593, 2021).
tumor (44 papers, 2005 to 2026). "Our study found six genes (PCNA, CDC6, CDC7, CDT1, CDK2, and RBBP8) that were most significantly linked with expression levels of key genes and tumor progression." (PMID 37656243, 2023). "A close association between RBBP8 and higher histological tumor grade (p = 0.041) was also confirmed by Fisher’s exact test." (PMID 29445424, 2018). "A close association between loss of nuclear RBBP8 protein and both advanced tumor stages and high-grade BLCA was significantly illustrated by a Fisher’s exact test." (PMID 29445424, 2018). "In fact, BRCA1 point mutations that abolish its interaction with CtIP/RBBP8 have been associated with tumor progression." (PMID 24403251, 2013). "Regulating the lncRNA cancer susceptibility 2 (CASC2)/miR-18a-5p/retinoblastoma binding protein 8 (RBBP8) axis could also suppress the tumor development." (PMID 37932756, 2023). "Further associations of RBBP8 methylation with clinicopathological characteristics were evaluated as well, which showed a significant association of RBBP8 methylation with higher histological tumor grade (p = 0.041)." (PMID 29445424, 2018). "Although some studies have found CtIP/RBBP8 to be mutated in tumor samples, and some general screenings using RT-polymerase chain reaction (PCR) have found changes in its mRNA levels (Oncomine), we describe here the first systematic study of the presence of CtIP/RBBP8 at the protein level." (PMID 24403251, 2013). "Mechanistically, RBBP8, a nuclear located protein that is conserved among vertebrates, interacts with tumor suppressors such as BRCA1 and the pRb family members through binding sites that are frequently mutated in human cancers." (PMID 29445424, 2018). "Nine out of 20 tumor (45%) samples showed a median RBBP8 methylation level (including all eight CpGs) of > 5% (range 6 to 62.5%)." (PMID 29445424, 2018). "Seventy-two hours after 5-aza-2′-deoxycytidine (decitabine (DAC)) and trichostatin A (TSA) treatment upregulation of RBBP8 mRNA expression (FC = 11) was demonstrated in RT4 tumor cells." (PMID 29445424, 2018). "Despite these connections with cancer, little is known about the role of CtIP/RBBP8 as a tumor suppressor gene itself." (PMID 24403251, 2013). "Strikingly, low expression of CtIP/RBBP8 correlated with a lower proportion of tumor relapse as compared to patients with normal CtIP/RBBP8 levels (P < 0.05)." (PMID 24403251, 2013). "Interestingly, we found for the first time that RBBP8 and MSH4 methylation and their corresponding gene downregulation were significantly associated with progressive UBC which is in parallel with high tumor stage and muscle-invasive disease." (PMID 36076047, 2022). "Unrepaired inter-strand crosslinks as consequence of reduced RBBP8 function may thereof sensitize tumor cells to chemotherapy treatment as well." (PMID 29445424, 2018). "RBBP8 methylation was confirmed to be tumor-specific in up to 45% of analyzed BLCA patients." (PMID 29445424, 2018). "Thus, we propose that CtIP/RBBP8 itself should be considered as a tumor suppressor." (PMID 24403251, 2013). "NDRG1 contributes to tumor aggressiveness by cell proliferation and lipid metabolism regulation, whereas GAPVD1, INPP5A, TCN1, SAV1, RBBP8, SPIB, and UBE2A also exhibit oncogenic or tumor-suppressive properties associated with prognosis." (PMID 41511940, 2026). "Representative protein expression of MEOX2, PHYHIP, RBBP8, ST18, TCF12, and THRB in tumor tissues was demonstrated based on immunohistochemical analysis in the HPA database." (PMID 40869909, 2025). "The list of genes with stringently tumor-specific hypermethylation includes, for instance, ERCC1, MGMT, POLD1, and RBBP8/CtiP." (PMID 29445424, 2018). "The genes most frequently targeted by MSI are RAD50 (16% of MSI-H tumours), ATR (15%) and RBBP8 (10%)." (PMID 28585546, 2017).
tumor (continued). "Relative expression levels of the eight genes of interest (AZGP1, BIRC5, DHCR7, IL6ST, MGP, RBBP8, STC2, and UBE2C) were compared between paired whole tissue sections and tumor-enriched specimens." (PMID 25218890, 2014). "CtIP/RBBP8 is a protein with a strong connection to cancer due to its functional and physical interactions with bona fide tumor suppressors." (PMID 24403251, 2013). "We have analyzed CtIP/RBBP8 and RB1 presence on all tumor samples and correlated their expression levels with cancer prognosis markers." (PMID 24403251, 2013). "The retinoblastoma binding protein 8 gene (RBBP8) is a predicted target of miR-31, miR-126, miR-130a, and miR-335 and is a putative tumor suppressor." (PMID 21461378, 2011). "In fact, a de novo search for such markers might be successful as we observed two genes, RBBP8 and MLL3, from our list of 84 genes whose expression was different in primary tumours of local recurrences as compared to controls." (PMID 31174485, 2019). "We detected three different CtIP/RBBP8 levels: level 0 contained samples in which no CtIP/RBBP8 could be detected with the antibody; level 1 represented an intermediate level; and level 2 corresponded to samples with a clear nuclear signal of CtIP/RBBP8 in more than 90% of the cells of the tumor." (PMID 24403251, 2013). "Thus, we reasoned that the tumor samples without CtIP/RBBP8 expression might correlate with an altered expression of RB1." (PMID 24403251, 2013). "MEOX2 and PHYHIP, showed no significant protein expression in tumor tissues; the THRB showed “low intensity”, RBBP8 and ST18 showed “medium intensity”, and, interestingly, the TCF12 showed “high intensity”." (PMID 40869909, 2025).
cancer (35 papers, 2012 to 2025). A tumor composed of atypical neoplastic, often pleomorphic cells that invade other tissues. "RBBP8 mutations are commonly detected in various human cancer cell lines." (PMID 33519915, 2020). "RBBP8/CtIP has a proven role in homologous recombination-mediated DNA double-strand break repair known to sensitize cancer cells for PARP1 inhibitors." (PMID 29445424, 2018). "In order to specify the TCGA data sets, we designed both a methylation-specific PCR (MSP) and bisulfite-pyrosequencing assay close to the TSS area to screen RBBP8 methylation status in a large set of normal and cancer cell lines from various cancer entities." (PMID 29445424, 2018). "Although we cannot discard that CtIP/RBBP8 protein levels are indeed increased in some samples, our data suggest that its contribution to cancer development is mainly due to its loss." (PMID 24403251, 2013). "Functionally, CtIP/RBBP8 transcriptional activity seems to contribute to cancer development and treatment success." (PMID 24403251, 2013). "From this, we conclude that patients with luminal cancer who have decreased CtIP/RBBP8 expression respond better to the combined hormone therapy, radiotherapy, and chemotherapy treatment than patients with normal or no CtIP/RBBP8 expression." (PMID 24403251, 2013). "Strikingly, when we analyzed the response of luminal cancers to a coadjuvant treatment with chemotherapy, we discovered that patients with low levels of CtIP/RBBP8 responded better." (PMID 24403251, 2013). "Normal CtIP/RBBP8 level cancers are usually grade 2, at a lower stage (T1), and less likely to present node metastasis." (PMID 24403251, 2013). "However, RBBP8 has been shown to play a role in the repair of DNA double strand breaks mediated by homologous recombination, which is known to make cancer cells sensitive to PARP1 inhibitors." (PMID 34356665, 2021). "In all other analyzed cancer types, RBBP8 methylation frequency was lower than 1.0%." (PMID 29445424, 2018). "Among the RNA targets that displayed a polysomal shift are mRNAs encoding proteins related to cancer, such as NRAS, the Ras-related protein R-Ras2, and those related to cell cycle, such as CDC27, the retinoblastoma binding protein RBBP8, and retinoblastoma-like 1 (RBL1)." (PMID 24842991, 2014). "However, low levels of CtIP/RBBP8 increase the response to chemotherapy in luminal cancers when combined with hormone therapy and radiotherapy." (PMID 24403251, 2013). "Based on mRNA studies, it has been proposed that CtIP/RBBP8 might be overexpressed in certain cancers, hence it was important to unequivocally determine which of the three levels corresponded to basal, nonpathological CtIP/RBBP8 protein expression." (PMID 24403251, 2013). "In fact, we propose that studying CtIP/RBBP8 expression could be used as a marker to define which cancers should be treated with chemotherapeutic agents." (PMID 24403251, 2013). "However, despite these associations with cancer, the expression level of RBBP8 has not been reported in PCM." (PMID 30622325, 2020). "Mutations in other HR genes, such as PALB2, RAD51C,RBBP8 (also known as CtIP), and BRIP1 (also known as FANCJ/BACH1), are also found in cancers." (PMID 39007266, 2024). "Further characterizing the role of RBBP8 and ATF4 in HCC pathogenesis by various transgenic mouse models will be helpful in developing therapeutics against HCC or other cancer types." (PMID 37591836, 2023). "Investigating the proteins driving cluster 1, we found lower levels of circulating proteins regulating DNA repair/integrity (RBBP8, RAD21) and cell fate/replication (NOTCH3, TJP3, HNRNPA2), which play a role in cancer development." (PMID 35033985, 2022). "Analyzing all the cancer biopsies for RB1 and CtIP/RBBP8 patterns revealed a strong statistically significant correlation between RB1 and CtIP/RBBP8: in more than 90% of those samples in which CtIP/RBBP8 was absent, RB1 was also either absent or reduced." (PMID 24403251, 2013).
cancer (continued). "On the other hand, CtIP/RBBP8 is a poor marker for predicting the overall response to treatment and cancer and disease-free survival." (PMID 24403251, 2013). "Second, although RB1 is reduced in those cancers without CtIP/RBBP8, it is likely that the cell cycle progression is affected." (PMID 24403251, 2013). "As many of the chemotherapeuticals act during S-phase, it would not be surprising that the amount of DNA lesions created is greatly reduced for cancers without CtIP/RBBP8, rendering the drugs less effective." (PMID 24403251, 2013). "Furthermore, since mutation of each of the five known Seckel genes, ATR, PCNT, CENPJ, CEP152 and RBBP8 (CtIP), cause genomic instability that is associated with apoptosis, it is possible that Seckel cells may not have the opportunity to accumulate cancer-causing mutations." (PMID 23166506, 2012). "The relationship between cancer and RBBP8 has not been fully studied." (PMID 30622325, 2020). "A protein with a strong but not completely explored cancer connection is CtIP/RBBP8." (PMID 24403251, 2013). "However, the relationship between cancer and RBBP8 has not been fully studied." (PMID 30622325, 2020).
RBBP8 also shares sentences with these, for which no sentence is quoted: colon cancer (5 papers); Fanconi anemia (4); infection (4); microcephaly (4); Jawad syndrome (3); lung carcinoma (3); plasma cell myeloma (3); prostate carcinoma (3); endometrial cancer (2); retinoblastoma (2); acute myeloid leukemia (1); alcoholic liver diseases (1); B cell lymphoma (1); bone cancer (1); cervical squamous cell carcinoma (1); cholangiocarcinoma (1); congenital microcephaly (1); cystitis (1); diffuse large B-cell lymphoma (1); ear tumors (1); esophageal carcinoma (1); familial breast cancer (1); fibrochondrogenesis 2 (1); glioma (1); head and neck squamous cell carcinoma (1); Hutchinson-Gilford progeria syndrome (1); Intellectual disability (1); intrahepatic cholangiocarcinoma (1); Mitosis (1); multiple myeloma (1).
A further 17 diseases each share a sentence with RBBP8 in 1 paper.